FZD6 (frizzled class receptor 6)
Diseases named in the same sentence as FZD6 in open-access papers (continued):
Sharing a sentence is not in itself a finding about the gene and the disease.
tumor (continued). "In the upregulated pairs, the B-cell leukemogenesis gene FZD6 and its ligand CTHRC1 were upregulated in several solid tumors, associated with increased cell migration and tumor invasion." (PMID 33777800, 2021). "For instance, the frizzled class receptor 6 (frizzled-6) of the Wnt pathway, responsible for NC induction, is also highly expressed in hypoxic areas on NB tumours, further linking NC development with NB and hypoxic conditions." (PMID 31861671, 2019). "FZD6 deleted cells showed impaired tumor initiation capacity, indicating the critical role of FZD6 in liver TICs." (PMID 29535420, 2018). "We subsequently found that the expression of FZD6 is suppressed in tumor tissues of PCa patients and down-regulation of FZD6 predicts poor prognosis." (PMID 29867083, 2018). "In the next chapter, we will review recent findings strongly suggesting that Fzd6 does play a role in tumour development and metastasis." (PMID 28737757, 2017). "Next, we performed immunohistochemical (IHC) staining for the expression of TCF4 and FZD6 in a separate cohort of 76 paraffin-embedded GBM tumours." (PMID 27698350, 2016). "The correlation between NKD1, FZD3 and FZD6 and β-catenin stabilisation indicates a cell autonomous effect in the tumour epithelium." (PMID 18414471, 2008). "Another study performed in liver tumor inducing cells showed direct binding of BRG1 at Fzd6 promoter during tumor inducing cell self-renewal, thereby providing additional support for BRG1 as a transcriptional regulator of genes encoding components of the Wnt pathway." (PMID 37484913, 2023). "Moreover, a significant correlation between FZD6 protein expression pattern and tumour grade (p = 0.04) was observed." (PMID 35237656, 2022). "Also, a significant correlation was observed between FZD6 expression profile and the tumour invasion property." (PMID 35237656, 2022). "Multivariate Cox regression analysis revealed that FZD6 expression pattern profile (low vs. high) in relation to the patients’ age, lymph node status, tumour grade, and vascular invasion was an independent poor survival factor for the DFS (p < 0.04) but not the DSS (p = 0.1)." (PMID 35237656, 2022). "In the veterinary literature, however, there is not yet evidence of FZD6 expression and its association with tumor progenitor and proliferation status, to the best of our knowledge." (PMID 34072517, 2021). "Thus, both ANKHD1 and FZD6 have well-characterized tumor cell-intrinsic roles, however, how they mediate their role in regulating tumor cell- extrinsic metastasis is not clear." (PMID 32245826, 2020). "FZD6 is also related to liver tumorigenesis, tumor metastasis and prognosis." (PMID 29535420, 2018). "Considering the role of FZD6 in Wnt/β-catenin activation is elusive, we overexpressed FZD6 in β-catenin inhibited cells, and found impaired influence on tumor invasion and self-renewal, indicating that FZD6 drives liver tumor invasion and liver TIC self-renewal through Wnt/β-catenin signaling." (PMID 29535420, 2018). "LncFZD6 drives liver TIC self-renewal and tumor initiation capacity through FZD6-dependent manner." (PMID 29535420, 2018). "We subsequently identified that FZD6 as a tumor suppressor suppresses the stemness of PCa cells." (PMID 29867083, 2018). "Notably, the expression of FZD6 has a strong correlation with tumor malignancy prognosis." (PMID 36712672, 2022). "Fzd1, Fzd2, Fzd6, Fzd9, and Fzd10 currently do not have any circRNA molecules associated with regulation of their expression, despite their obvious role in cancer signaling and tumor progression, highlighting the potential for future research." (PMID 34671643, 2021). "In addition, downregulation of FZD6 in tumor tissue predicts poor prognosis." (PMID 29867083, 2018). "Furthermore, we identified FZD6 as a tumor suppressor that can abolish PCa stemness." (PMID 29867083, 2018). "FZD2 and FZD6 play an important role in Wnt signalling, regulating epithelial–mesenchymal transformation (EMT) and tumour progression." (PMID 40045484, 2025).
tumor (continued). "Specifically, the FZD1, FZD2, FZD6, FZD7, and FZD8 genes were found to be significantly overexpressed in tumor tissues compared to normal pancreatic tissues, based on mRNA expression data from TCGA and other public databases." (PMID 40943055, 2025). "Secreted WNT5A was suggested to interact with a wide range of tumor cell-expressing receptors, such as LRP5, LRP6, FZD5, and FZD6." (PMID 40524253, 2025). "Especially, a panel of WNT components, including WNT5A, WNT7B, GPC1, and FZD6 or FZD7, shows tumor tissue-specific increment in CSCC, HNSC, LUSC, and BTCC." (PMID 35850748, 2022). "Initial findings indicated that RANGAP1, GOPC, NHLRC3, FZD6, and IDE were significantly correlated with stem cell indices and tumor microenvironment parameters." (PMID 35859893, 2022). "Consistent with the observed increase in WNT related genes in tumor cells, we saw high scores for WNT-related interactions (ligands Sfrp1 and Wnt5a and receptors Fzd6, Fzd7 and Lrp6) and significant BMP-related interactions (e.g. from Bmp4 with Bmpr1a)." (PMID 35600339, 2022). "The analytical results showed that FZD6 and CTHRC1 were both highly expressed in the B cells of tumor samples." (PMID 33777800, 2021). "We found increased expression of FZD6, FZD7, RYK, and PTK7 in tumors, as well as a highly significant increase in FZD7 in tumor-adjacent cells." (PMID 31261741, 2019). "Indeed, RNAi knockdown of FZD6 in MDA-MB-231 triple negative breast cancer cells inhibited their motility and caused reduction of bones and liver metastases, suggesting that activation of the PCP pathway is critically important for metastatic dissemination and tumour tropism in vivo." (PMID 28737757, 2017). "To test the importance for tumor growth and metastasis of these genes we introduced inducible cDNAs of CDK6, CDK14 and Fzd6 alone or in combination into the parental ES cell line of the β-Catenin driven model, 91C5, and generated chimeric mice." (PMID 25162504, 2014). "At the receptor level, immunohistochemical (IHC) analysis has revealed significantly increased expression of FZD6 in CRC tumor samples compared to adjacent non-cancerous tissue." (PMID 40943055, 2025). "Other targets of miR-199a that may affect tumor proliferation and metastasis are ROCK1, HIF1α, BCAM, FZD6, and DDR1." (PMID 36499729, 2022). "Corroborating to this, Eμ-TCL1 animals lacking the Fzd6 gene show decreased levels of beta-catenin and delay in tumor growth." (PMID 33659046, 2021). "Moreover, several tumor suppressors, including BTG2, TUSC1, BAK1, LATS2, FZD6 and PPP2R1B, were regarded as common targets of TET3." (PMID 32209730, 2020). "Comparing the survival rate of the three tumor subtypes separately and considering their FZD6 expression levels, an obvious but not significant difference was revealed." (PMID 33255843, 2020). "Furthermore, we identified tumour suppressors, including BTG2, TUSC1, BAK1, LATS2, FZD6 and PPP2R1B, as common targets of TLX and TET3." (PMID 26838672, 2016). "Interestingly, some genes were already known to have a biological role in tumourigenesis, either as tumour suppressors (such as TUSC3) or elements of critical importance within tumour growth pathways (i.e., SFRP1 and FZD6, belonging to the Wnt signalling pathway)." (PMID 35327445, 2022). "FZD6 has a known role in non-canonical WNT/PCP signaling in cancer, including mediating transformation, increased invasiveness of tumor cells and metastasis." (PMID 32245826, 2020).
cancer (47 papers, 2013 to 2025). A tumor composed of atypical neoplastic, often pleomorphic cells that invade other tissues. "Interestingly, mutations affecting the molecular switch of FZD6, specifically R6.32A and R6.32Q/L, with R6.32Q/L being naturally occurring cancer mutants of FZD6, show impaired recruitment of DVL." (PMID 39198452, 2024). "Then, risk scores were calculated for every cancer sample calculated by using the following formula: Riskraw = DAD1*2.316+CYCS*1.426+CSNK2A2*1.576+VPS25*0.728+VDAC1*0.976+TMLHE*0.381+CYTH3*0.024+PRKCA*0.260-TP73*0.567+FZD6*0.047+SQSTM1*0.094-MAP2K7*3.070." (PMID 35185897, 2022). "Luga and colleagues demonstrated that exosomes secreted by cancer-associated fibroblasts can instigate breast cancer cells to acquire a motile phenotype by mobilizing PCP core components such as FZD6, DVL1, VANGL1, PK1 and stimulating the autocrine secretion of the non-canonical ligand Wnt11." (PMID 28737757, 2017). "For example, FZD6 is upregulated in several cancers, where its enhanced PCP signaling promotes epithelial-to-mesenchymal transition (EMT), a critical step in metastasis." (PMID 40376615, 2025). "Other notable proteins, such as ACKR3, COL11A1, CPA4, and FZD6, were previously reported as potential therapeutic targets in cancer." (PMID 38652547, 2024). "siRNA-mediated depletion of FZD6 enhanced the motility of SNU601 cells, and addback of FZD6 restored cancer cell motility stimulated by miR-199a/b." (PMID 37838767, 2023). "Nevertheless, we detected a panel of 10 prospective biomarkers, including FZD6, which is the regulator of the Wnt pathway in different cancer types." (PMID 35566209, 2022). "When treated with luteolin, a dietary flavonoid with anti-cancer activity, FZD6 expression increased, and the stem phenotype decreased." (PMID 34604862, 2021). "Fzd6 is connected with many cancer types, including breast, liver, prostate, colorectal, and lung cancers and leukemia." (PMID 34671643, 2021). "The activation of Wnt4/FZD6 involves in the different diseases such as cancer, embryonic development, bone marrow mesenchymal stem cell dysfunction." (PMID 32616722, 2020). "Focusing on FZD6, it becomes obvious that R416Q6.32 is the most prevalent variant associated with cancer in Class F receptors." (PMID 30737406, 2019). "On the other hand, results from several studies indicated that FZD6 serves as oncogene that promotes cancer development." (PMID 29867083, 2018). "Interestingly, WNT4 expression in these cancers is accompanied by increased levels of FZD6 and MYC, i.e., features that we detected in aggressive TETs previously." (PMID 35965500, 2022). "On the contrary, Golan T and his colleagues found that human Fzd6 could act as a negative regulator of the Wnt/β‐cat signaling by inhibiting the ability of β‐catenin to activate the transcription in human 293 T and cancer cell lines." (PMID 34056869, 2021). "Expression of the gene coding Fzd6 molecule was found to be higher in some human cancers, such as colorectal carcinoma, hepatocellular carcinoma, SCC and prostate cancer; however, there is no information about its possible association with canine oral neoplastic lesions." (PMID 34072517, 2021). "Some of the transcription factors that were specifically expressed in OS-DW cells were ATF6, CDX2, FOSL1, PRDX3, FZD6, MYNN, TRAF1 which are known to regulate pathways implicated in cancers like, Wnt/Hedgehog/Notch signaling, MAPK signaling, Apoptosis and mTOR signaling." (PMID 31690262, 2019). "The mutation of W7.55 to L in FZD2, FZD6 and SMO is associated with different forms of cancer." (PMID 30737406, 2019). "However, the FZD6 functions as an inhibitor of cancer cell transformation by negatively regulating canonical Wnt/β-catenin signaling pathway." (PMID 23390598, 2013). "Hence, FZD6 was suggested as a promising therapeutic cancer target." (PMID 35237656, 2022). "Time will tell whether Fzd6 targeting has a future in cancer therapeutics." (PMID 28737757, 2017).
cancer (continued). "The function played by Fzd6 in the physiology of normal and cancer cells has been highlighted in the view that an increased knowledge of the signalling pathways upstream and downstream of this receptor could ultimately result in the identification of new targets for cancer therapy." (PMID 28737757, 2017). "The WNT signaling in our study is altered by the deregulation of APC, FZD1, FZD6, LRP6, and WNT10B, which are included by KEGG in the process of cancer proliferation." (PMID 34715892, 2021). "Beyond this, the pathway in cancer revealed that most of the genes are relative to WNT pathway (WNT7B, WNT6, WNT10B, FZD6, FZD8, and LPAR5), and among these, WNT7B, WNT10B, FZD6, FZD8, and LPAR5 belonged to the classical WNT pathway." (PMID 34122668, 2021). "Conversely, 28 of cancer-related genes were downregulated by shNrf1, of which 6 genes (i.e., HIF1A, STAT5B, IGF1R, TGFBR1, ATRN, and FZD6) were upregulated by Nrf1α−/− to varying extents." (PMID 32273945, 2020). "FZD6 and FZD3 are the most highly expressed Wnt receptors in the cancer cell lines." (PMID 41286306, 2025). "The PCP pathway, mediated by FZD3 and FZD6, further amplifies non-canonical Wnt signaling’s role in cancer progression." (PMID 40376615, 2025). "FZD6 may present a unique scenario among FZD receptors, where it contributes to both promotion and suppression of EMT depending on the cancer type and could be a target for highly personalized delivery of chemoprevention." (PMID 34604862, 2021). "Both the experimental FZD6 R416A6.32 and the naturally occurring cancer mutants of the molecular switch R416Q6.32 and W493L7.55 were impaired in the ability to recruit DVL to the membrane and to induce the electrophoretic mobility shift associated with DVL activation 50,51." (PMID 30737406, 2019). "In addition to the experimental R/K6.32 to alanine mutants, we have also performed mG BRET experiments using the naturally occurring cancer mutants FZD6 R416Q6.32 and SMO R455H6.32, as well as FZD6 W493L7.55 and SMO W539L7.55." (PMID 30737406, 2019). "The role of FZD6, the other upregulated protein, in the pathogenesis of cancer is not clear." (PMID 41226368, 2025). "Furthermore, we aimed in the present study to evaluate the expression of nestin, NGFR, Sox10, FZD6 and PROM1 cancer stem cell markers and angiogenic factors in UM and to better understand the relationships between the detected markers and vasculogenic mimicry patterns." (PMID 33255843, 2020). "These genes have various implications for cancer therapy, and the detailed mechanism of action of DLG3, TGFB3, TGFBR1 and FZD6 genes in GC has not been studied, and needs further researches to explore." (PMID 36712672, 2022). "We observed the overexpression of isoforms of genes C3orf17, FRMD4A, FZD6, HNRNPA2B1, POSTN, PRKAA1, RRBP1 and VEGFA, and the under expression of TRIP12 isoform (ENST00000428959) in ACC patients who are not free of cancer, which is a surrogate for poor ACC outcomes." (PMID 33035235, 2020).
infection (3 papers, 2017 to 2025). The state of being infected such as from the introduction of a foreign agent such as serum, vaccine, antigenic substance or organism. "DU145 cells expressing the doxycycline-inducible FZD6 shRNA were infected with the lentivirus expressing the kinome gRNAs at a multiplicity of infection (MOI) of 0.3." (PMID 41286306, 2025). "Conversely, after inhibitor infection, Hif1a (p=0.048), Fzd6 (p<0.01), and Gcnt2 (p<0.01) were increased and Atg14 (p=0.042) increased." (PMID 38770735, 2024). "If anything, there was a decrease in the proportion of quiescent HSCs in Fzd6-/- bone marrow on day 28, correlating with their previously reported self-renewal defect, and indicating that the Fzd6-/- bone marrow responded to the infection." (PMID 28787450, 2017). "To further investigate the impact of HSPC expansion on downstream myeloid differentiation during infection, we evaluated the acquisition of regulatory markers by Fzd6-/- Ly6Chi monocytes." (PMID 28787450, 2017). "However, expansion was blunted in Fzd6-/- mice on day 28 post-infection, which corresponds to the peak of expansion." (PMID 28787450, 2017). "We further demonstrate that the expansion is functionally important, as monocytes generated in the presence of soluble factors extracted from the infected bone marrow are more permissive to infection, and a stunted emergency response such as seen in Fzd6-/- mice results in decreased parasite burden." (PMID 28787450, 2017). "However, there was an improvement in parasite control 72h post-infection in the presence of IFNγ, suggesting that Fzd6-/- bone marrow macrophages could partially contribute to the decreased parasite burden." (PMID 28787450, 2017). "Fzd6-/- mice display no specific defects in the bone marrow MPC compartment at steady state or on day 14 post-infection, prior to the parasite-induced changes in hematopoiesis." (PMID 28787450, 2017).
nervous system diseases (1 paper, 2019). "In conclusion, NPTX2, a molecule related to nervous system diseases, promotes CRC cell proliferation and metastasis through the activation of the Wnt/β-catenin pathway via direct interaction with FZD6." (PMID 30833544, 2019).
FZD6 also shares sentences with these, for which no sentence is quoted: pancreatic adenocarcinoma (2 papers); adult T-cell leukemia (1); amyotrophic lateral sclerosis (1); anaplastic thyroid cancer (1); COVID-19 (1); ductal breast carcinoma (1); embryonal carcinoma (1); hemorrhage (1); influenza infection (1); lip (1); lipoma (1); lymphoma (1); meningocele (1); metastatic cancer (1); Obesity (1); osteosarcoma (1); schizophrenia (1); squamous cell carcinoma (1); ulcerative colitis (1).